SLED1 (proteoglycan 3, pro eosinophil major basic protein 2 pseudogene )
Gene: Long non-coding RNA gene on chromosome 4 (184,798,296 to 184,799,046, reverse strand). Ensembl gene ENSG00000293200.
Diseases named in the same sentence as SLED1 in open-access papers:
SLED1 is named in the same sentence as 1 disease in open-access papers, as found by Europe PMC text mining. Sharing a sentence is not in itself a finding about the gene and the disease. The quoted sentences say what the papers report.
systemic lupus erythematosus (1 paper, 2021). An autoimmune multi-organ disease typically associated with vasculopathy and autoantibody production. "AC007032.1 is associated with immunomodulatory cytokine Nampt, while SLED1 was found up regulated in peripheral blood cells of systemic lupus erythematosus patients." (PMID 33509158, 2021).